EZH2 (enhancer of zeste 2 polycomb repressive complex 2 subunit)
Diseases named in the same sentence as EZH2 in open-access papers (continued):
Sharing a sentence is not in itself a finding about the gene and the disease.
melanoma (continued). "EZH2 expression was found to decrease in response to BRN2 siRNA knockdown in all three melanoma cell lines, reduced to levels of 0.4 fold or lower across all three lines tested compared to the negative siRNA control cells." (PMID 28119061, 2017). "A total of 138 cases of melanoma samples harboring BRAF V600E mutation were included, and EZH2 copy numbers were examined by QuantiGenePlex DNA Assays." (PMID 29202777, 2017). "Our data suggests that increased melanoma cell migration in response to elevated NFIB is in part achieved through EZH2 mediated down-regulation of MITF expression." (PMID 28119061, 2017). "Combination with BRAF and EZH2 inhibition showed better inhibitory efficacy in melanoma prevention compared with vemurafenib monotherapy." (PMID 29202777, 2017). "More importantly, this improved therapeutic effect was observed especially in melanoma cell lines and PDX models containing concurrently BRAF V600E mutation and EZH2 gain." (PMID 29202777, 2017). "For example, the miR-31 locus is frequently lost in melanoma samples and this is correlated with invasion and metastasis of melanoma, in particular because of its regulatory relationship with Enhancer of zeste homolog 2 (EZH2)." (PMID 29112174, 2017). "Intriguingly, in the context of glucose restriction, tumors are able to impair T cell functionality in ovarian cancer and melanoma models trough miR101 and miR26a (EZH2 repressors)." (PMID 29112174, 2017). "Inhibition of EZH2 through GSK343 treatment resulted in a significant decrease in melanoma cell migration in the A2058-empty MM96L− empty control cells when compared with the vehicle (DMSO) control cells." (PMID 28119061, 2017). "We demonstrated that combination therapy was more efficacious than single agent alone in vitro and in vivo, whereas only in melanoma cell lines and PDX models concurrently containing BRAF V600E mutation and EZH2 gain." (PMID 29202777, 2017). "The co-occurrence of BRAF and EZH2 hyperactivation as illustrated in the precision medicine case in melanoma presented above opens new possibilities for targeted treatment." (PMID 28265786, 2017). "Our findings provided evidence for the feasibility of combination therapy with EZH2 and BRAF inhibitors in melanoma with concurrent BRAF V600E mutation and EZH2 gain." (PMID 29202777, 2017). "Accordingly, inactivation of histone-lysine N-methyltransferase EZH2 with a preclinical inhibitor impaired proliferation and invasiveness accompanied by re-expression of tumor suppressor genes in melanoma cells." (PMID 28978033, 2017). "EZH2 is essential for melanoma initiation and growth, during which EZH2 and Ki-67 positive cells significantly correlate, just like in the BC model." (PMID 27239242, 2016). "Increased expression of EZH2 in melanoma strongly correlates with shorter overall survival (OS) and earlier development of distant metastases." (PMID 27239242, 2016). "In this study, we have utilized both ectopic expression of EZH2 GOF mutations and a small molecule inhibitor of EZH2 to gain insight into the function of EZH2 and EZH2 GOF mutants in solid tumor biology with a particular focus on melanoma." (PMID 25671303, 2015). "EZH2 is an important driver of melanoma progression and EZH2 inhibitors promising therapeutic agents." (PMID 26322273, 2015). "The current report is the first to evaluate the potential of EZH2 inhibitors as a therapeutic strategy in human melanoma." (PMID 26304929, 2015). "This also appears to be the case in melanoma; in which EZH2 and H3K27me3 were found to be upregulated in both EZH2Y646 mutant and WT cell lines, compared to normal cells." (PMID 26304929, 2015). "The 3D cultures showed that GSK126 treatment reduced infiltration of cells into collagen which is consistent with the increased mobility reported in A375 melanoma cells transfected with EZH2." (PMID 26304929, 2015).
melanoma (continued). "This study supports an important role for EZH2 catalytic activity in melanoma and warrants further study of the utility of EZH2 inhibitors within this disease setting." (PMID 25671303, 2015). "Further studies are needed to validate these genes as bonafide EZH2 targets whose expression is repressed by aberrant methylation in melanoma." (PMID 26304929, 2015). "EZH2 function can be inhibited by a number of small molecules and EZH2 inhibition in melanoma reduces cell growth and metastases." (PMID 26426052, 2015). "Specifically in melanoma, we have delineated a novel pathway regulated by both ectopically and endogenously expressed EZH2 GOF mutants: the axonal guidance pathway." (PMID 25671303, 2015). "Treatment with the EZH2 inhibitor GSK126 effectively reduced the levels of H3K27me3 in melanoma cell lines in a dose dependent manner, leading to a reduction in proliferation, cell cycle arrest and apoptosis." (PMID 26304929, 2015). "Inhibition of the histone methyltransferase and PRC2 member EZH2 leads to melanoma cell death by induction of AIF (apoptosis inducing factor) release from mitochondria." (PMID 26426052, 2015). "They provide further support for EZH2 as a promising therapeutic target in melanoma treatment, especially in EZH2Y646 mutants." (PMID 26304929, 2015). "The observation that EZH2 inhibitor-treated IGR1 cells displayed a similar morphological reversion in 3D culture points toward conserved functions of EZH2 GOF mutants across melanoma cell lines." (PMID 25671303, 2015). "We show that inhibition of EZH2 has potent effects on the growth of both wild-type and EZH2 mutant human melanoma in vitro particularly in cell lines harboring the EZH2Y646 activating mutation." (PMID 26304929, 2015). "Additionally RPPA data from the TCGA showed that melanoma patients with activated EZH2 (somatic mutation, copy number gains or mRNA activation) show significantly decreased levels of NDRG1_pT346, supporting the hypothesis that aberrant EZH2 activity represses tumor suppressor genes in cancer." (PMID 26304929, 2015). "Here, we show that SSX2, a germline-specific protein ectopically expressed in melanoma and other types of human cancers, is a chromatin-associated protein that antagonizes BMI1 and EZH2 PcG body formation and derepresses PcG target genes." (PMID 25249625, 2014). "Highest EZH2 activation is seen in neuroblastoma, hepatocellular carcinoma, small cell lung cancer, and melanoma, while highest HDAC activity is seen in pharyngeal cancer, kidney cancer, and pancreatic cancer." (PMID 24079712, 2013). "We next measured the expression levels of EZH2 mRNA and protein in a large cohort of melanoma samples." (PMID 22948084, 2012). "EZH2 protein was determined in situ by immunohistochemistry utilizing melanoma tissue microarrays (TMA) and individual sections consisting of benign nevus (n=16), dysplastic nevus (n=13), primary melanoma (n=66) and metastatic melanoma (n=127) samples." (PMID 22948084, 2012). "Next, treatment of five different melanoma cell lines with deazaneplanocin A (DZNep), a compound that, which depletes EZH2 and other polycomb repressive complex 2 (PRC2) components and thus attenuates H3K27me3, led to the induction of miR-31 in all cell lines." (PMID 22948084, 2012). "Quantitative RT-PCR analysis demonstrated that EZH2 mRNA was overexpressed in metastatic melanomas (n=71) relative to primary melanocyte cultures (p-value =0.002)." (PMID 22948084, 2012). "Moreover, we found that miR-31 also engages in an antagonistic regulatory circuit with EZH2, and loss of miR-31 expression may contribute to EZH2 overexpression in melanoma and provides a potential therapeutic axis which can be targeted by small molecule inhibitor." (PMID 22948084, 2012).
melanoma (continued). "EZH2 expression showed significant prognostic impact in melanoma, prostate, and endometrial carcinoma in univariate survival analyses, but revealed independent multivariate prognostic importance only in carcinoma of the endometrium and prostate." (PMID 20920340, 2010). "EZH2 inhibitor plus MEK inhibitor provide a promising therapeutic strategy for NRASmut melanoma." (PMID 41492362, 2026). "TFAP2A derived melanoma metastasis by regulating E2F and EZH2." (PMID 40813717, 2025). "Through the integrated analysis of single‐cell state and lineage, they determined that EZH2 may regulate gene expression involved in the cell‐state transitions of melanoma cells into dedifferentiated cell states composed of high‐memory genes." (PMID 40491322, 2025). "In this system, MPNST cells show refractory capacities to induce melanocytic trans-differentiation upon melanoma-promoting signaling cues, such as canonical Wnt signaling gain of function or increased of levels of the epigenetic mark H3K27Me3 upon Ezh2 gain of function." (PMID 41063628, 2025). "In melanoma, lncRNAs regulate EZH2 activity, thereby influencing tumour progression." (PMID 41463281, 2025). "The most studied EZH2 inhibitor in melanoma is Tazemetostat." (PMID 40427015, 2025). "Likewise, a study on mucosal melanoma overcame resistance mechanisms to ferroptosis and showed tumour growth inhibition by combining EZH2 inhibition with erastin, a ferroptosis inducer." (PMID 40143107, 2025). "Moreover, ATRX is described to interact with EZH2, which has already been confirmed as a direct target of miR-101-3p in melanoma." (PMID 38431560, 2024). "Moreover, in an in vitro model of mouse cutaneous melanoma, pharmacological inhibition of EZH2 significantly reduced melanoma progression and decreased invasiveness, thereby leading to increased survival." (PMID 38473991, 2024). "Our findings suggest that targeting the EZH2 pathway could offer a new therapeutic approach to treating mucosal melanoma, potentially improving patient outcomes." (PMID 39518098, 2024). "For instance, lncRNA PVT1 was found to be differentially expressed in cutaneous melanoma, which revealed that lncRNA PVT1 might promote the tumorigenesis and metastasis of melanoma by binding to EZH2 and regulating miR-200c expression." (PMID 39659781, 2024). "Indeed, EZH2 inhibition reduces proliferation in melanoma cells and reduces tumor growth in a mouse model of melanoma." (PMID 39409910, 2024). "As a result, EZH2 has been shown to regulate the progression of melanoma by negatively regulating a number of tumor suppressor genes (TSGs) implicated in cell transformation and proliferation, evasion of senescence and apoptosis, as well as increased invasiveness and metastasis." (PMID 38473991, 2024). "Similarly, in melanoma, the expression of p21CIP is inhibited by the epigenetic regulator EZH2, and EZH2 knockdown in melanoma cells rescues p21CIP expression." (PMID 38561743, 2024). "Future studies are warranted to investigate whether EZH2 might regulate ferroptosis via the GPX4 pathway in mucosal melanoma, further broadening the therapeutic potential of targeting EZH2 in ferroptosis-related cancer treatments." (PMID 39518098, 2024). "Next, we examined the copy number of the EZH2 gene in 547 melanoma samples." (PMID 39518098, 2024). "Notably, the copy number amplification rate of the EZH2 gene in MM was significantly higher than that in other melanoma subtypes (p < 0.001)." (PMID 39518098, 2024). "One important target in the epigenetic therapy of melanoma is EZH2." (PMID 38473991, 2024). "The EZH2 high-melanoma patient group showed a significantly shorter survival." (PMID 39518098, 2024). "EZH2 depletion activates p21 and induces senescence in melanoma." (PMID 38804044, 2024). "UBR4-mediated EZH2 degradation has also recently been reported in melanoma cells." (PMID 39394462, 2024).
melanoma (continued). "Further analysis in 11 melanoma cell lines revealed that the protein expression levels of EZH2 in cell lines with EZH2 copy number gain (GAK, LM-MEL-53, and A375) were significantly higher than those within the normal range (SK-MEL-5), though not uniformly across all cell lines." (PMID 39518098, 2024). "Additionally, mir-16 directly targets oncogenes like BMI1 and EZH2, promoting melanoma development and metastasis." (PMID 39061157, 2024). "Additionally, in a poorly immunogenic melanoma model, the inhibition of EZH2 triggered the expression of STING and consequently sensitized cancer cells to STING agonists." (PMID 36900330, 2023). "Emerging evidence indicates that long non-coding RNAs (lncRNAs) are molecular “address codes” for EZH2 silencing specificity, and targeting lncRNAs-EZH2 interaction may slow down the progression of many solid cancers, including melanoma." (PMID 37325482, 2023). "Finally, recent research paper has depicted EZH2 as a key regulator of pigmentation and melanoma plasticity, since EZH2 expression negatively correlates with melanocyte inducing transcription factor (MITF)." (PMID 37325482, 2023). "Moreover, in melanoma, BRAF mutations are linked to a high expression of EZH2, which is associated with melanoma progression, worse patient survival, and resistance to MAPK inhibitors." (PMID 37510333, 2023). "To understand discrepancies between EZH2 mRNA and EZH2 protein levels in melanoma cells, we investigated post-translational mechanisms that might regulate EZH2." (PMID 36906655, 2023). "However, in 39 melanoma samples obtained from patients in the Melanoma Research Victoria cohort, incrementally increasing EZH2 protein expression was observed from early stage to metastatic disease, confirming published data." (PMID 36906655, 2023). "Emerging evidence indicates that EZH2 is contributing to progression of melanoma." (PMID 37325482, 2023). "Moreover, in melanoma, the oncogene enhancer of zeste homolog 2 (EZH2) has been shown to be a main molecular player in the silencing of ciliary genes during melanoma development." (PMID 37510333, 2023). "If EZH2 positively regulates malignant behaviors in melanoma cells, then its expression might be predicted to increase during disease progression." (PMID 36906655, 2023). "EZH2 histone methyltransferase is highly expressed and installs the H3K27me3 histone mark at tumor suppressor genes, thereby inhibiting their expression to drive the development and metastasis of melanoma." (PMID 37293029, 2023). "In addition, treatment with vemurafenib in combination with the EZH2 inhibitor GSK126 has been shown to result in improved inhibitory efficacy in vitro and in vivo compared with vemurafenib alone in BRAFi-susceptible melanoma." (PMID 36768289, 2023). "The authors of this report speculate that increased expression of EZH2 during melanoma immunotherapy with anti-CTLA-4 antibodies or IL-2 triggers diminution of therapy efficacy." (PMID 37325482, 2023). "It has been demonstrated that LNMAT1 promotes migration and invasion of melanoma in vitro and in vivo by cooperating with EZH2 to inhibit the expression of cell adhesion molecule 1 (CADM1), a recognized tumor suppressor that inhibits the expression of MMP-2 and MMP-9 matrix metalloproteinases." (PMID 37325482, 2023). "This is the first-time investigation of mutated EZH2 in BTC and in a solid tumor beside melanoma." (PMID 36900361, 2023). "We outline the involvement of lncRNAs-EZH2 interaction in cancer focusing on melanoma." (PMID 37325482, 2023). "Subsequently, EZH2 protein levels, as well as consecutive accumulation of H3K27me3, are reduced, thereby impairing tumor progression, as demonstrated in colon, breast, hepatocellular, and nasopharyngeal cancers, as well as melanoma and glioblastoma." (PMID 35565249, 2022).
melanoma (continued). "Other recent findings suggest that EZH2 could interact with DNA methyltransferases (DNMT) to mediate robust silencing of its target genes in melanoma, including the IFN-γ pathway." (PMID 35432344, 2022). "The downregulation of TRAIL in BCR-ABL1-positive cells is mediated by a preferentially expressed antigen of melanoma (PRAME)/enhancer of zeste homolog 2 (EZH2) repression mechanism, and the inhibition of either PRAME or EZH2 expression increases TRAIL levels and sensitivity to TRAIL and to imatinib." (PMID 35057108, 2022). "Although the mechanisms by which SWI/SNF exerts tumor suppression in melanoma have not been clearly delineated, they may involve antagonism with EZH2, a validated oncogene in melanoma." (PMID 35323214, 2022). "The single VUS in EZH2 (p.F642L) was adjacent to the melanoma hot spot (p.Y646F)." (PMID 35229492, 2022). "Therefore, pharmacological inhibition of EZH2 is an engrossing target in various cancers including melanoma." (PMID 36224606, 2022). "EZH2 inhibits the immunogenicity and antigen presentation of melanoma cells." (PMID 35907846, 2022). "In melanoma, elevated EZH2 contributes to a shift to a more invasive and metastasizing phenotype." (PMID 35163453, 2022). "The EZH2, H3K27me3-specific histone methyltransferase enhancer of zeste 2 polycomb repressive complex 2 subunits, is the other deregulated histone-modifying enzyme during the melanoma initiation and progression." (PMID 36224606, 2022). "The same group reported that H3K27me3′s expression in melanoma was highly correlated with tumor thickness and may represent a good marker to analyze EZH2′s activity as well as the PRC2 complex subunits." (PMID 36230787, 2022). "The IHC staining and the quantitation analysis revealed that compared to the normal skin tissue, USP7 and EZH2 were highly expressed but FOXO1 was expressed at a lower level in melanoma samples, and the expression levels of USP7 with EZH2 or FOXO1 were correlated with cancer progression." (PMID 33849069, 2021). "Moreover, EZH2 and H3K27me3 are overexpressed in highly invasive melanoma cells and metastatic melanomas, leading to TSGs inactivation." (PMID 34575678, 2021). "Notably, the use of EZH2i in the treatment of wild-type and mutant melanoma cell lines led to a reduction in cell proliferation and growth, legitimating EZH2 as a veritable target in melanoma cells." (PMID 34575678, 2021). "Besides, EZH2 is important for melanoma progression as aberrations are found in 27% of patients, and it is associated with invasive melanoma." (PMID 34944799, 2021). "Interestingly, EZH2 seems to play a role in melanomagenesis, given that its expression increases from benign melanocytic proliferations to malignant melanoma." (PMID 34440824, 2021). "Focal amplifications of EZH2 were also identified in 5.7% of melanoma cases from TCGA database." (PMID 34831002, 2021). "Moreover, conditional ablation of EZH2 in a melanoma mouse model impaired tumor growth and attenuated metastasis without affecting the functionality of normal melanocytes." (PMID 34575678, 2021). "Another point of reference, to aid in our understanding of the role of G9a in melanoma, is the array of literature on EZH2, which is the target of the first FDA approved histone methyltransferase inhibitor, tazemetostat, for the treatment of epithelioid sarcoma." (PMID 34691767, 2021). "In addition, immunotherapy combined with CPI-1205 treatment exerts an improved anticancer function via the modification of EZH2 expression in melanoma." (PMID 34001246, 2021). "Finally, it is also worth mentioning that EZH2 gain-of-function mutations usually co-occur with BRAF V600E mutations in CM, promote aggressive cell morphologies and enhance melanoma tumor growth in vitro." (PMID 34575678, 2021). "Overexpression of lncRNA GAS5 or CDKN1C or EZH2 knockdown could inhibit cell viability but enhance melanoma cell apoptosis and oxidative stress." (PMID 32308561, 2020).